IL6 (interleukin 6)
Diseases named in the same sentence as IL6 in open-access papers (continued):
Sharing a sentence is not in itself a finding about the gene and the disease.
depression (continued). "Moreover, increased IL-6 and TNFα and lower serum zinc levels are associated with risk for depression and treatment-resistant depression." (PMID 22747645, 2012). "Furthermore, GTS-associated recovery from LPS-induced depression-like behavior was paralleled with reduced mRNA levels for IL-1β, IL-6, TNF-α, and IDO in hippocampus." (PMID 21843370, 2011). "Notably, IL-6 has been implicated as a key mediator of cancer-related depression." (PMID 41149069, 2025). "In addition to symptoms associated with gland dysfunction, interleukin 6 (IL-6) may play a role in the development of depression." (PMID 40822847, 2025). "In models adjusted for age, sex, and race, we found greater risk of decline among those with history of depression treatment, higher body mass index (BMI), preexisting functional impairment, frailty (by index), and higher baseline high-sensitivity C-reactive protein and interleukin-6 levels." (PMID 40519631, 2025). "At higher IL-6 levels, the buffering effect of social support may be especially pronounced, alleviating inflammation-induced disruptions in neurobiological processes implicated in depression, such as HPA axis dysregulation and serotonin depletion." (PMID 41210298, 2025). "Exercise is known to modulate depression-related biomarkers, including interleukins (IL) such as IL-6, a key component of the immune and inflammatory systems, and other molecular signatures associated with MDD pathophysiology." (PMID 40665827, 2025). "Additionally, dietary fiber may be inversely associated with depression through various inflammatory markers such as the C‐reactive protein and interleukin‐6 (IL‐6), according to several studies." (PMID 40678325, 2025). "IL-6, a key cytokine in neurogenesis and synaptic plasticity, plays a vital role in normal brain function, and its inhibition has been associated with increased susceptibility to depression and cognitive impairments, including memory deficits and executive dysfunction." (PMID 40094890, 2025). "Importantly, the study also showed that depression-associated DNAm changes were correlated with the levels of inflammation markers in plasma, including IL-6, and that changes in the major histocompatibility complex (MHC) region have a causal relationship with depression." (PMID 40637488, 2025). "Additionally, it would be valuable to examine whether 40 Hz tVAS affects plasma biomarkers associated with depression, such as brain-derived neurotrophic factor, interleukin-6, and cortisol." (PMID 40860215, 2025). "In addition, while most studies were purely descriptive, a subset integrated biological markers into NA models, revealing significant associations among fatigue, depression, sleep disturbances, and inflammatory biomarkers such as IL-6, CRP, and tumor necrosis factor-α." (PMID 40633921, 2025). "Furthermore, another study found that an IL6R functional variant could reduce inflammation, and high serum levels of IL-6/IL6R can increase the severity of depression." (PMID 41274868, 2025). "However, increased proinflammatory cytokines may contribute to the anxious status in mice with sleep deprivation because blood inflammatory cytokines, such as IL-6, is associated with psychiatric symptoms including depression and anxiety in man." (PMID 41202022, 2025). "Our finding that increasing IL-6 levels were associated with increasing severity of depressive symptoms may be explained by the effect of IL-6 on biological systems previously linked to depression." (PMID 39902492, 2025). "While this measure could be useful for studying the biological functions of IL-6, possibly trans-signalling in particular, it remains unclear whether this measure is associated with the clinical and cognitive features of depression that have previously been linked with inflammation." (PMID 38442505, 2024).
depression (continued). "We report associations of a novel, multi-protein-derived biomarker of IL-6 activity/bioavailability with several clinical and cognitive outcomes in a sample of individuals with depression including somatic symptoms, fatigue, depression severity, and psychomotor speed." (PMID 38442505, 2024). "In addition, the intake of EM reduced the abundance of Ruminococcaceae promoting the production of cytokines such as IL-1β, IL-2, and IL-6, Helicobacter inducing chronic inflammation and gastric cancer, and Alistipes causing serotonergic imbalance, anxiety and depression." (PMID 39572022, 2024). "Thus, the IL6 rs1800795-C (promoter) genomic variant is associated with the predisposition to depression onset in Australian and Spanish populations, and also correlates with increased sensitivity to pain and stress perception in a Hungarian population of depressed patients." (PMID 38646100, 2024). "Thus, the objective of this research was to understand whether homocysteine and/or the inflammatory cytokines IFN-γ, TNF-α, IL-6, and IL-1β, may be associated with depression improvement in veterans with GWI after one month on the low-glutamate diet." (PMID 39064698, 2024). "This type of depression is linked to increased pro-inflammatory cytokines such as interleukin 6 (IL-6), tumor necrosis factor alpha (TNF-α), C-reactive protein (CRP), and several other factors, and these inflammatory factors may help distinguish between inflammatory and non-inflammatory depression." (PMID 38589368, 2024). "Furthermore, polymorphisms in the IL-1β, TNF-α, and C-reactive protein may increase the risk of depression, and single nucleotide polymorphisms (SNP) in the IL-1β, IL-6, and IL-11 genes may be associated with decreased efficacy of anti-depressant treatment." (PMID 36768580, 2023). "Thus, findings of our study indicate that inflammation is associated with GDM, and IL-6 could be the potential contributor to the development of stress and depression in GDM." (PMID 37365247, 2023). "The diathesis-stress model for the development of MDD partly accords with this possibility, and the disruption of the IL-6 diurnal rhythm, influenced by the individual’s genetic predispositions and the intensity of environmental stress, might be a key predictor for depression." (PMID 37324818, 2023). "We found CSF IL-6 to have a considerable mediating role in depressive symptoms, which is compatible with previous evidence consistently implicating IL-6 in the risk for depression, although our study is one of the first to demonstrate this specifically in the context of HIV." (PMID 37280232, 2023). "However, the elevation of IL-6 may be associated not only with chronic inflammation but also with other pathological processes that may also be observed in depression." (PMID 36899845, 2023). "The IL6-174G/C polymorphism was associated with the severity of symptoms of current depressive disorder, with recent stress on current depressive symptoms, with lifetime depression, and with mean scores on the AA subdomain of the Positive and Negative Syndromes Scale in patients with schizophrenia." (PMID 37510364, 2023). "In addition, both the WBH and sham WBH groups received enough heating to raise core body temperature, likely reducing our ability to demonstrate that the association of the acute IL-6 response with reductions in depression was specific to participants randomized to WBH." (PMID 37085494, 2023). "Together, these results suggest that while generalized inflammation may not be responsible for the associations of smoking and depression, the IL-6 pathway specifically may warrant further investigation as a potential biological mechanism underlying the effect of smoking on depression." (PMID 36057695, 2022).
depression (continued). "However, we do not find evidence for a potentially causal role for CRP on depression or for potentially mediating role for CRP on the association between smoking and depression, though we did find evidence for a potentially mediating role for IL-6 activity on this association." (PMID 36057695, 2022). "Furthermore, FMT from RA patients caused depression-like phenotypes, alterations of gut microbiota composition, increased levels of IL-6 and tumor necrosis factor-α (TNF-α), and downregulation of synaptic proteins in the PFC compared to FMT from healthy controls." (PMID 35650202, 2022). "Furthermore, we have carried out MR analysis in the full sample, and in men and women separately, to test whether associations of CRP and IL-6 with depression and anxiety are consistent with potential causal roles for these biomarkers in these conditions." (PMID 34505025, 2021). "IL-6 activates the hypothalamic-pituitary-adrenal axis activity and increases the plasma concentrations of adrenocorticotropic hormone and cortisol, which induce multiple adverse immunological changes that make patients with depression susceptible to infection." (PMID 34711196, 2021). "Increased inflammation as a risk factor for depression in adolescents was also reported in the recent meta-analysis where increased CRP and IL-6 were associated with subsequent MDD development in children and adolescents." (PMID 34816138, 2021). "Altered activity of the IL-6/IL-6R pathway could be a risk factor for depression." (PMID 34505025, 2021). "Using MR analyses, we provide evidence that higher IL-6 activity could represent a potential causal factor increasing depression, while genetically predicted higher CRP concentrations appeared to potentially be protective for depression and anxiety, which contrasts findings for serum CRP." (PMID 34505025, 2021). "A special role in the pathogenesis and somatic consequences of MDD has been described for pro-inflammatory IL-6, whose activity may cause depression through the activation of the hypothalamic-pituitary-adrenal axis or influence of the neurotransmitter metabolism, as summarized elsewhere." (PMID 33763446, 2021). "While our findings suggest that altered activity of the IL-6/IL-6R pathway could be a risk factor for depression, disentangling the issue of IL-6 classic vs trans-signalling is beyond the scope of population genomics approaches as full effects of genetic variants used are unknown." (PMID 34505025, 2021). "Hence, IL-6 classic signalling may potentially underlie protective findings for schizophrenia and depression." (PMID 34135474, 2021). "The IL-6/IL-6R pathway could be causally linked to depression." (PMID 34135474, 2021). "Moreover, IL-6 has been identified as an important susceptibility gene for major depression." (PMID 31362361, 2019). "Population-based longitudinal studies show that higher levels of CRP and IL-6 at baseline are associated with an increased risk of depression in subsequent follow-ups, suggesting that inflammation could be a cause rather than simply a consequence of the illness." (PMID 31258105, 2019). "Age-related chronic low-grade inflammation is associated with elevations in circulating interleukin-6 and tumor necrosis factor-α, and they have been reported as a common factor for the occurrence of sarcopenia as well as and the development of cognitive impairment and depression." (PMID 29845019, 2018). "Moreover, we found that depression symptoms after stroke were associated with the low serum vitamin D levels and elevated serum IL‐6 levels, which indeed provides evidence for the hypotheses about the underlying mechanism of PSD." (PMID 29484258, 2018). "Moreover, SLC6A4 is significantly related with both increased depressive symptoms and elevated IL-6 plasma levels suggesting that common phathophysiological processes may be associated with depression and inflammation." (PMID 30127739, 2018).
depression (continued). "The significant reductions in plasma IL-6 levels after 6-months in the HT group points to the possibility that elderly adults with inflammatory diseases associated with high IL-6 levels such as depression, dementia, rheumatoid arthritis and cancer could garner benefits from HT." (PMID 30096932, 2018). "Work on the Whitehall II cohort shows that individuals with increased IL-6 levels over a prolonged period of time (one, two, or three measurements over a 5-year period) have an elevated subsequent 10-year risk for development of cognitive symptoms of depression." (PMID 29181395, 2017). "Indeed, a previous study of 33 adults with a lifetime history of depression (assessed with the 9-item Patient Health Questionnaire), reported that IL6 methylation was inversely associated with circulating IL6 (and C-reactive protein), but only for individuals with lifetime depression." (PMID 29070016, 2017). "However, one population-based study showed how participants with increased levels ofsystemic inflammation in childhood, indicated by higher serum levels of interleukin-6,were at significantly increased risk of developing depression in adulthood (Khandakeret al.2014)." (PMID 27181594, 2016). "Furthermore, IL-6 influenced the development of depression in fibromyalgia patients, and a meta-analysis also demonstrated elevated IL-6 levels associated with the prevalence of depression, and inversely correlated with survival rates in patients with malignant tumors." (PMID 26821321, 2016). "Moreover, a recently published review concluded that IL-6 is the cytokine most robustly associated with suicidal ideation, suicides, and nonfatal suicide attempts, thereby suggesting an important role of this interleukin in this aspect of depression." (PMID 27918465, 2016). "Regarding the pathophysiology of depression, it has been proposed that environmental factors—mainly stress—can exert their depressogenic effects through neuroinflammatory signalling mechanisms, and stress-induced depressive conditions were associated with significantly higher IL-6 levels." (PMID 26821321, 2016). "Indeed, in a recent study, we found that both depression and hopelessness were associated with systemic inflammation, assessed by interleukin-6 in plasma, and this effect remained for hopelessness after adjustment for depressive symptoms, but not for depression after adjustment for hopelessness." (PMID 24430130, 2015). "One previous meta-analysis assessing the association between CRP, IL-6 and depression employed more relaxed inclusion criteria and sample material which may partially explain the smaller overall effect size estimates described in that study (CRP, d = 0.15 and IL-6, d = 0.25)." (PMID 26065825, 2015). "Several biological mechanisms including decreased heart rate variability, increased platelet aggregation, higher levels of inflammatory risk markers (C-reactive protein and interleukin-6) among individuals with depression and/or anxiety may lead to increased risk for cardiovascular diseases." (PMID 24433257, 2014). "Interestingly, depressed individuals also show exaggerated release of inflammatory mediators in response to psychosocial stressors, implying altered immunoregulation, and epidemiological studies in the UK showed that raised CRP and IL-6 predict subsequent risk of depression." (PMID 24481186, 2013). "Elevated IL-6 level may increase risk of depression development in patients with ESRD." (PMID 22972567, 2013). "A cancer diagnosis itself may lead to posttraumatic stress disorder (PTSD), causing depression and anxiety as well as an increased level of biomarker expression, such as interleukin-6 (IL-6), tumor necrosis factor-α (TNF-α), cortisol, and high-reactive sensitive C-reactive protein." (PMID 24285975, 2013). "Moreover, raised CRP and IL-6 predicted subsequent risk of depression." (PMID 24481186, 2013).
depression (continued). "A large-scale meta-analysis indicated that levels of TNF-α, IL-6, IL-1RA are elevated in patients with depression, while IFN-γ levels tend to decrease." (PMID 41601490, 2026). "Research shows IL‐6 is crucial in neuro‐immune crosstalk in pancreatic cancer—tumor and surrounding cells secrete IL‐6, which promotes tumor survival, drug resistance, and systemic symptoms like muscle wasting (cachexia), depression, and fatigue." (PMID 41583906, 2026). "Elevated levels of CRP (p = 0.0038), hs-CRP (p = 0.0048), and IL-6 (p = 0.0030) were identified in the anxiety group, while the depression group was characterized by reduced vitamin D levels (p = 0.0302)." (PMID 41750331, 2026). "In regression analyses, depression was associated with TNF-α (β = -0.133 to -0.152) and IL-6 (β = -0.171 to -0.207)." (PMID 41600880, 2026). "For example, changes in IL-6 serum levels have been reported as one of the most consistent abnormalities in both depression and cancer." (PMID 41491244, 2026). "A clinical study comparing healthy controls and patients with IBD found that those with symptomatic IBD exhibited the highest depression and anxiety scores, along with elevated intestinal IL-6, interleukin-1β (IL-1β), and serum IL-6 expression levels." (PMID 41590739, 2026). "Elevated pro-inflammatory cytokines, including tumor necrosis factor-α (TNF-α), interleukin-1β (IL-1β), and interleukin-6 (IL-6), have been observed in both patients and animal models of depression." (PMID 41535967, 2026). "The second study, conducted in a Korean cohort receiving Lactobacillus reuteri and Bifidobacterium adolescentis, reported significant improvements on the Beck Depression Inventory-II and reduced interleukin-6 levels." (PMID 40869419, 2025). "Research on the molecular processes of RA and depression has identified shared immunological pathways and overlapping inflammatory cytokines, including IL-1, IL-18, and IL-6." (PMID 40958218, 2025). "Depression, anxiety, fatigue, IL-6, and tumor necrosis factor-α had higher strength centrality indices and were identified as the most central nodes within the symptom-biomarker networks." (PMID 40633921, 2025). "The increase in pro-inflammatory cytokines IL-6 and IL-2 affects depression and anxiety in a neuromodulatory way, mediating the neurochemical, neuroendocrine, and behavioral aspects of mental health disorders." (PMID 40563433, 2025). "Hesperidin (20, 50, and 100 mg/kg orally for 28 days) reduces depression-like behaviors and expression of IL-1β, IL-6, TNF-α, NLRP3, caspase-1 in the prefrontal cortex and microglia in chronic unpredictable mild stress (CUMS)-induced rats." (PMID 40703750, 2025). "Low HDL-C levels have been connected to low-grade inflammation, mediated by interleukin-6, which is prevalent in depression." (PMID 40511456, 2025). "The inflammatory cytokine levels in MDD patients remained lower than schizophrenia, yet IL-6 and IL-1β showed significant links to depression intensity." (PMID 40416228, 2025). "The anti-inflammatory effects of these beverages are thought to stem from their ability to lower levels of inflammatory markers such as C-reactive protein (CRP) and IL-6, which are often elevated in individuals with depression." (PMID 40004109, 2025). "These individuals were retained in the analysis as they contribute to the relationship between IL-6 and depression, and a key advantage of multilevel models is that it uses FIML to account for missing outcome data." (PMID 39865800, 2025). "Alongside traditional self-reported assessments of pain intensity, functional disability, quality of life, depression, anxiety and stress, the trial incorporates objective physiological markers such as cortisol, β-endorphins, substance-P, IL-6, CRP and HRV." (PMID 40510459, 2025).